DPP4 (dipeptidyl peptidase 4)
Diseases named in the same sentence as DPP4 in open-access papers (continued):
Sharing a sentence is not in itself a finding about the gene and the disease.
myopathy (1 paper, 2024). A disease of the muscle in which the muscle fibers do not function properly. "It is suggested that the DPP-4 inhibitory potential of vitamin D3 is responsible for the amelioration of MetS-induced metabolic changes and myopathy." (PMID 39356321, 2024). "This work aims to examine the efficacy of vitamin D3 in inhibiting MetS-induced myopathy and to determine whether the beneficial effects of vitamin D3 are mediated by the inhibition of dipeptidyl peptidase-4 (DPP-4)." (PMID 39356321, 2024).
neuromuscular disease (1 paper, 2022). "Our data reveal the crucial role of Bap1-mediated SMN stabilization in Dpp4+ FAPs for the neuromuscular system and provide the possibility of cell-based therapeutics to treat neuromuscular diseases." (PMID 35603786, 2022).
DPP4 also shares sentences with these, for which no sentence is quoted: mesothelioma (22 papers); acute myocardial infarction (11); gastrointestinal stromal tumor (9); adenocarcinoma (8); atopic dermatitis (6); gastrointestinal tumors (6); thyroid (6); benign prostatic hyperplasia (5); glomerulosclerosis (5); Sézary syndrome (5); anaphylaxis (4); Hepatitis (4); kidney injury (4); neuroblastoma (4); proliferative diabetic retinopathy (4); rectal cancer (4); thalassemia (4); vascular dementia (4); aspiration pneumonia (3); cholangitis (3); chronic pancreatitis (3); colorectal tumor (3); graft versus host disease (3); Headache (3); metastatic melanoma (3); Osteopenia (3); polyp (3); respiratory failure (3); sarcoma (3); T-lymphoblastic lymphoma (3).
A further 215 diseases each share a sentence with DPP4 in 3 papers or fewer.